SOCS3 (suppressor of cytokine signaling 3)
Diseases named in the same sentence as SOCS3 in open-access papers (continued):
Sharing a sentence is not in itself a finding about the gene and the disease.
Obesity (174 papers, 2007 to 2026). Accumulation of substantial excess body fat. "STAT3 and SOCS3 play important roles in the downstream pathway of IL-6 and are associated with muscle atrophy in obesity and diabetes." (PMID 38561446, 2024). "An epigenome-wide association study on obesity identified three notable loci: cg18181703 (SOCS3), cg04502490 (ZNF771), and cg02988947 (LIMD2)." (PMID 39498440, 2024). "Thirdly, more studies with a larger sample size are necessary to unravel the exact role of SOCS 1 and SOCS3 in obesity-associated metabolic abnormalities." (PMID 36609306, 2023). "The study also intended to assess the possible association of SOCS1 and SOCS3 transcript levels with metabolic parameters in the context of obesity." (PMID 36609306, 2023). "Although the current study cannot address the underlying mechanism regarding the role of SOCS1 and SOCS3 in obesity and associated metabolic dysfunction, the possible mechanism can be derived from in vitro and murine model surveys." (PMID 36609306, 2023). "Animal model studies suggest that change in the members of the suppressor of the cytokine signaling (SOCS) family (mainly SOCS1 and SOCS3) is linked to the pathogenesis of obesity-related metabolic disorders." (PMID 36609306, 2023). "Data from in vitro studies and animal models point to the possible role of SOCS1 and SOCS3 in underlying mechanisms pertinent to obesity and associated metabolic disorders." (PMID 36609306, 2023). "We also intend to identify the possible association of SOCS1 and SOCS3 transcript levels with metabolic parameters in the context of obesity." (PMID 36609306, 2023). "Socs3, Mmp9 and Prmt1, which had elevated expression levels in obesity that were reversed by weight loss, had decreased expression in ABA and remained decreased in WR." (PMID 37582711, 2023). "Three types of Mendelian randomization methods were implemented to examine the potential causality between SOCS3 methylation and obesity based on the SNP of SOCS3 as instrumental variables." (PMID 36145200, 2022). "One study in the Northern European population pointed out that the association of SOCS3 methylation level with obesity was significantly inverse." (PMID 36145200, 2022). "The high increase in TNF-α is associated with obesity and IR, through the up-regulation of SOCS3 (suppressor of cytokine signaling 3)." (PMID 35008925, 2022). "Studies have shown that single nucleotide polymorphisms in SOCS3 gene are closely related to obesity and BMI." (PMID 34991691, 2022). "Among the top 10 significant DEGs, IL15 and SOCS3 were found to be upregulated in obese asthmatics compared with non-obese asthmatics, which have been previously reported as obesity-associated marker genes." (PMID 34576307, 2021). "Obesity provides major attenuation of NFκB signaling via SOCS3-associated JAK2 inhibition, and then suppresses WNK4 activity." (PMID 34489970, 2021). "Dimerized STAT3 acts as a transcription factor and upregulates SOCS3 expression, which can induce hypothalamic leptin resistance linked to obesity." (PMID 33379198, 2020). "Possible leptin resistance developed during obesity can be attributed to the decrease in transport of leptin across the blood-brain barrier as well as an increase in the inhibitor SOCS3 (typically associated with diet-induced obesity in mice)." (PMID 32742493, 2020). "In contrast, the coding region of SOCS3 which is associated with obesity-related cancers, was hypomethylated in obesity and CRC." (PMID 30911103, 2019). "In the same study, rs4969172 (SOCS3) was also investigated for association with multiple obesity-relate traits phenotypes (including BMI, and waist circumference), but none was found." (PMID 30886629, 2019). "IKKβ/NF-κB and ER stress promote each other during HFD intake, induce leptin resistance by up-regulating SOCS3, and promote the energy imbalance underlying obesity." (PMID 31739649, 2019).
Obesity (continued). "Only SOCS3 has previously been investigated in humans, and few studies have found evidence of an association with obesity-related phenotypes." (PMID 30886629, 2019). "As a direct transcriptional product of STAT3, SOCS3 is commonly thought to play a pathophysiological role in obesity-associated leptin resistance." (PMID 29615796, 2018). "While hepatic SOCS3 deficiency initially prevents impaired insulin action in diet-induced obesity, these mice have accelerated inflammation at later stages." (PMID 30591653, 2018). "In our results, SOCS3 was the only obesity-associated gene whose protein regulated all three of the most enriched KEGG pathways." (PMID 30619480, 2018). "The heterozygous SOCS3-deficient mouse was more sensitive to the weight-reducing effects of leptin and was resistant to the development of diet-induced obesity." (PMID 28881823, 2017). "Some of the single nucleotide polymorphisms (SNPs) on SOCS3 were previously shown to be related to obesity and type 2 diabetes mellitus in adults although the exact functional mechanisms are unclear." (PMID 27611604, 2016). "Consistently, leptin-deficient mice develop severe obesity, whereas SOCS-3 conditional knockout mice are resistant to diet-induced obesity." (PMID 27716333, 2016). "This points to dysregulation of the leptin-SOCS-3 axis, especially in obese individuals, and to a possible obesity-related pathogenic mechanism in OA." (PMID 27716333, 2016). "Elevated SOCS-3 expression in the CNS is proposed to be the primary mechanism that causes leptin resistance and subsequent failure in controlling food intake in obesity." (PMID 27716333, 2016). "Although polymorphisms in suppressor of cytokine signaling 3 (SOCS3) was reported to be related to obesity, Metabolic syndrome (MS), and type 2 diabetes mellitus in various adult studies, there is a lack of data in children." (PMID 27611604, 2016). "Mice with deficient SOCS3 expression in adipose tissues were protected against the development of obesity-associated insulin resistance." (PMID 24600449, 2014). "In the central nervous system obesity-associated inflammation can disrupt leptin hypothalamic action through IKKβ/NFkβ regulation of SOCS-3 (suppressor of cytokine signaling-3), a key inhibitor of leptin signaling." (PMID 23672628, 2013). "SOCS3 production in fat is associated with obesity in humans and rodents as SOCS3 gene expression is increased in subcutaneous fat of obese patients, and its protein and gene expression levels are increased in epididymal fat of DIO rodents." (PMID 22871059, 2012). "In the context of obesity, IL-6 is intricately associated with chronic inflammatory processes and contributes to the inhibition of hepatic insulin signaling through the induction of SOCS3 protein expression." (PMID 40519917, 2025). "Inaccessibility of the hypothalamus has made it impossible to determine whether SOCS3 expression in key target cells influences susceptibility to obesity in humans." (PMID 38165042, 2024). "Moreover, the loss of SOCS3 is believed to be driven by the alteration of SOCS3 methylation states triggered by specific lifestyles, including obesity." (PMID 36078084, 2022). "We hypothesized that polymorphisms in genes involved in the hypothalamic IKKβ/NF-κB signaling pathway (NFKB1, IKBKB, and SOCS3), alone or in interaction with nutrients, are associated with energy imbalance and obesity pathogenesis in humans." (PMID 30886629, 2019). "In this study, we investigated gene–gene and gene–environment interactions in the association between variants of three genes (NFKB1, IKBKB, SOCS3), macronutrient and alcohol intakes, and obesity-related phenotypes (BMI, alternative BMI cut-offs for East and South Asians, and waist circumference)." (PMID 30886629, 2019). "On the other hand, it has also been considered controversial whether the obesity-associated SOCS3 CpG impacts the transcription level." (PMID 30619480, 2018).
Obesity (continued). "In this context, suppressor of cytokine signaling 3 (SOCS3) seems to be a key protein in central leptin resistance because its loss of function in the hypothalamus confers protection to high-fat diet (HFD)-induced obesity." (PMID 28321206, 2017). "SOCS3 has also been linked to the development of leptin resistance during obesity." (PMID 29025435, 2017). "Moreover, PTP1B and SOCS3 contribute to the development of leptin resistance: Their expression in the hypothalamus is increased by diet-induced obesity, and their deficiency protects mice from the development of leptin resistance." (PMID 28912580, 2017). "In addition, there is evidence for association between variants located near SOCS3 with glucose homeostasis, BMI, and other obesity traits." (PMID 26823690, 2016). "For instance, while increased expression of hypothalamic Socs3 and Lrgrp are hallmark features of diet-induced obesity and key factors in the development of common leptin resistance, the expression of these genes is not altered or tended to be lower in BBS mice." (PMID 26926121, 2016). "Obesity is associated with overexpression of SOCS3 in human and rodent skeletal muscle." (PMID 27746742, 2016). "However, mice with haploinsufficiency of SOCS3 showed enhanced leptin sensitivity and were protected against the development of diet-induced obesity and associated metabolic complications." (PMID 27542279, 2016). "To test this hypothesis, we characterized muscle SOCS3 expression in response to metabolic challenges known to be associated with insulin and/or leptin resistance such as high-fat diet feeding, genetic obesity, lipid infusion, and TNFα injection." (PMID 23115649, 2012). "Given the importance of leptin in body weight regulation, this study was undertaken to determine whether variations in the coding sequence (CDS) or promoter region of SOCS3 are associated with early onset obesity in a German population." (PMID 17445271, 2007). "We hypothesized that genetic variations, leading to an altered expression or function of SOCS3 could affect energy homeostasis through an influence on leptin signaling and thus predispose an individual towards the development of obesity." (PMID 17445271, 2007). "In oncogenic diseases, such as glioblastoma multiforme, an increase in methylation of the SOCS3 gene has been detected, with a subsequent decrease in its expression, whereas overexpression of SOCS3 has been associated with changes in circulating miRNAs in children with obesity." (PMID 36674935, 2023). "In addition, obesity has been associated with downregulation of SOCS3, which raises the possibility that an association between DNAm near SOCS3 and liver dysfunction could result from the well described relationship between obesity and liver dysfunction." (PMID 36303554, 2022). "Therefore, the hyper-methylation of SOCS3 in the gene promoter and its nearby region silences the inhibitory effect on leptin and insulin of SOCS3, whereas hyper-methylation in the gene body facilitates it to inhibit the activity of insulin and leptin, resulting in a high risk of obesity." (PMID 36145200, 2022). "However, this study is the first to investigate gene–gene and gene–environment interactions between polymorphism in NFKB1, IKBKB, SOCS3, macronutrient and alcohol intakes, in the association between overnutrition and obesity-related phenotypes in human subjects." (PMID 30886629, 2019). "At the same time, berberine treatment reduced the gene and protein levels of SOCS3 and improved obesity-induced leptin resistance." (PMID 41588470, 2026). "In diet-induced obesity, microglial SOCS3 is elevated, but STAT3 activation in response to leptin is blunted, while NF-κB-driven inflammation persists, demonstrating selective resistance." (PMID 41516046, 2025). "Conversely, the deletion of SOCS3 in hypothalamic neurons has demonstrated improvements in leptin sensitivity, a reduction in appetite, and protection against diet-induced obesity." (PMID 40283443, 2025).
Obesity (continued). "This study also makes brain Socs3 a potential therapeutic target for treating leptin resistance, type 2 diabetes and obesity." (PMID 40755762, 2025). "Previously, the gut microbiome has been indicated to interplay with Socs3 gene expression and function in conditions such as myeloid hematopoiesis and obesity." (PMID 40387487, 2025). "Overexpression of SOCS3 has been observed in microglia from obesity models, which can serve as a marker of leptin resistance." (PMID 41516046, 2025). "Socs3 is upregulated in obesity and inhibits leptin and insulin signaling, while its downregulation reduces hepatic lipid levels in obese Sprague–Dawley rats." (PMID 40535017, 2025). "Reticuline inactivates the JAK2/STAT3/suppressor of cytokine signaling-3 (SOCS3) and p38 subgroup of mitogen-activated protein kinases (MAPKs)/NF-κB signaling pathways in obesity-related asthma." (PMID 41415580, 2025). "Reticuline alleviates airway inflammation in obesity‐related asthma by inactivating the JAK2/STAT3/SOCS3 and p38 MAPK/NF‐κB signaling pathways." (PMID 38286741, 2024). "Although SOCS3 is an attractive target for treatment of obesity, its general inhibition would likely have adverse effects because SOCS3 inhibits signaling by many cytokines." (PMID 38165042, 2024). "In some investigations, it is shown that increased BMI, body weight gain, and obesity are related to increased SOCS3 expression." (PMID 36609306, 2023). "Among SOCS family members SOCS1 and SOCS3 have received special attention in the pathogenesis of different disorders like immune disorders, tumorigenesis, type 2 diabetes, and obesity." (PMID 36609306, 2023). "Taken together, these findings suggest that states of metabolic endotoxemia and inflammation induced by high-fat diets lead to increased concentrations of SOCS3, thereby leading to leptin resistance and contributing to hyperphagia and obesity." (PMID 37571301, 2023). "It has been documented that in obesity SOCS3 is upregulated in concert with increases in inflammation in the hypothalamus, adipose tissue, and liver." (PMID 37511764, 2023). "Similar effects were observed in central IKKb knockout mice and, in the MBH, SOCS3 overexpression decreased the neural IKKb inhibition effect on obesity reduction." (PMID 36899905, 2023). "SOCS3 is part of the natural feedback loops controlling leptin signaling, and is a strong mediator of leptin and insulin resistance in obesity." (PMID 36674520, 2023). "Although the current study as a preliminary one opens an avenue to the involvement of SOCS1 and SOCS3 in the obesity etiology, however, several limitations merit comment." (PMID 36609306, 2023). "Reduced SOCS3 expression in adipose tissue is protective against high-fat diet induced obesity and insulin resistance." (PMID 37571301, 2023). "After bisulfite treatment of DNA, methylation-specific PCR was used to assess the putative methylation of 10 CpG sites in the promoter of SOCS1 and 13 CpG sites in SOCS3 in SAT from women with obesity and normal weight." (PMID 36609306, 2023). "Studies have confirmed that, in the neurons of the hypothalamus in mice, SOCS3 knockout leads to an improvement in central leptin signaling and reduced obesity." (PMID 36899905, 2023). "Evidence on the subject has found that in POMC neurons, overexpression of the unfolded protein response transcription factor (Xbp1s) decreases the expression of PTP1B and SOCS3, improves leptin and insulin sensitivity, and protects against obesity." (PMID 35563589, 2022). "Mice with haploinsufficiency of Socs3 display greater leptin sensitivity than wild-type mice and are protected against the development of diet-induced obesity." (PMID 34523036, 2022). "Afterward, based on TFEA and qRT-PCR verification, we confirmed that SOCS3, ICAM-1, NT5E, MYC, CCL2, and PPARG were potential ORDEGs that linked obesity and OLF pathogenesis." (PMID 35712246, 2022).
Obesity (continued). "A short-term decrease of SOCS3 in the liver improves insulin sensitivity; however, long-term suppression of SOCS3 induces metabolic syndromes such as hyperglycemia and obesity." (PMID 35626153, 2022). "Previous studies have focused on the relationship between the methylation level of cg18181703 SOCS3 and obesity." (PMID 36145200, 2022). "This study deciphered immune/inflammatory signatures of obesity-related gene clusters for the first time, and defined SOCS3 as one core gene." (PMID 35712246, 2022). "Obesity also activates the suppressor of cytokine signaling-3 (SOCS-3), which lowers the sensitivity of the vagal nerve’s afferent branch, encouraging carcinogenesis." (PMID 36059323, 2022). "Matthew E Talbert also found that SNPs rs2280148 in SOCS3 gene is closely related to various types of obesity in the American population." (PMID 34991691, 2022). "Topological analysis and modular analysis revealed the role of HJJPD in the treatment of simple obesity by acting on SOCS-3, JAK2, LepRB, LEP, IL-6, and STAT3 and influencing the JAK2-STAT3 pathway." (PMID 35529938, 2022). "On one hand, persistent external factors, such as obesity-related systemic inflammation, induce DNA hypermethylation, and in turn, genome-wide repression of target genes including m6A modifiers and SOCS3." (PMID 35712246, 2022). "A case–control study in young women summarized that the methylation levels of cg18181703 in SOCS3 (chr17: 76354621) significantly differed between obesity and lean individuals (−0.245 (−0.332, −0.142), p < 0.05)." (PMID 36145200, 2022). "A study conducted in a community population in New Haven revealed that subjects with obesity had lower methylation levels of SOCS3." (PMID 36145200, 2022). "This loop of SOCS3 overexpression in obesity and resultant inhibition of STAT3/NFκB activation probably explain the attenuation of VILI observed within the first hours in our diet-induced obese mouse model." (PMID 34489970, 2021). "Mutation of the STAT3-recruiting tyrosine 1138 on the LepRb prevented SOCS3 feedback inhibition of leptin signalling, while overexpression of a constitutively active version of STAT3 in POMC neurons elevated Socs3 expression and led to obesity." (PMID 34502119, 2021). "Rodents with Socs3 deletion in proopiomelanocortin (POMC) neurons are resistant to diet‐induced obesity and have lower levels of circulating leptin." (PMID 34057306, 2021). "Alternatively, a lentiviral mediated knockdown of SOCS3 within the hypothalamus is protective against diet-induced obesity in rats." (PMID 34613819, 2021). "Another particular adipokine, resistin, was shown not only to be increased in circulation during obesity, but also to synergize with leptin on SOCS3 upregulation in various tissues." (PMID 33924072, 2021). "This also suggests that SOCS3 only partly accounts for the upregulation of the WNK4–SPAK cascade in obesity." (PMID 34489970, 2021). "SOCS3 is upregulated in patients with obesity and impedes the signal transduction of STAT3 via simultaneous binding to JAK and the gp130 cytokine receptor." (PMID 34489970, 2021). "Mice exhibiting haploinsufficiency of Socs3 are partially protected from both obesity and leptin resistance in response to high-fat feeding." (PMID 34502119, 2021). "Obesity protects lungs from VILI by upregulating SOCS3, thus suppressing the STAT3/NFκB inflammatory pathway and enhancing WNK4-related AFC." (PMID 34489970, 2021). "After VILI, the activation of WNK4 in mice was slightly modulated by obesity and the manipulation of SOCS3 expression." (PMID 34489970, 2021). "The suppressor of cytokine signaling 3 (SOCS3) is an overexpressed protein that leads to leptin resistance in patients with obesity." (PMID 34489970, 2021). "SOCS3 was upregulated in obesity; it hindered the JAK2–STAT3/NFκB cascade immediately after mechanical stretching." (PMID 34489970, 2021).